GPX4 (glutathione peroxidase 4)
Diseases named in the same sentence as GPX4 in open-access papers (continued):
Sharing a sentence is not in itself a finding about the gene and the disease.
renal cell carcinoma (24 papers, 2017 to 2026). "For instance, a study of sensitivity profiling in 177 cancer cell lines revealed that diffuse large B cell lymphomas and renal cell carcinomas were susceptible to GPX4‐regulated ferroptosis." (PMID 41541703, 2026). "Cells of thyroid origin are more sensitive to GPX4 loss than nearly all other lineages in the Cancer Dependency Map, including renal cell cancers, which have been touted for their intrinsic ferroptosis sensitivity." (PMID 37262067, 2023). "According to a sensitivity profiling in 177 cancer cell lines, renal cell carcinomas (RCCs) and diffuse large B cell lymphomas (DLBCLs) are particularly susceptible to GPX4-regulated ferroptotic cell death." (PMID 35118067, 2021). "Hereditary Leiomyomatosis and Renal Cell Carcinoma (HLRCC): FH inactivation causes fumarate accumulation, protein succination, and GPX4 dysfunction." (PMID 41425591, 2025). "For example, decreased KLF2 attenuated ferroptosis in renal cell carcinoma by regulating GPX4 level." (PMID 37874682, 2023). "Icariside II is a flavonoid with antitumor properties, which directly suppresses the GPX4 through miR-324-3p to induce ferroptosis, thus inhibiting the migration and invasion of renal cell carcinoma (RCC)." (PMID 37369681, 2023). "Specifically, knockout of GPx4 by siRNAs reduces the level of GPx4 protein (GPx4 protein is the central mediator of ferroptosis) and then leads to the death of renal cell carcinoma cells, accompanied by the production of lipid ROS." (PMID 37007068, 2023). "GPX4-regulated ferroptosis inhibited tumor growth in a xenograft mouse model, and knockdown of GPX4 sufficiently killed renal cell carcinoma cell lines." (PMID 35151318, 2022). "They found that the diffuse large B cell lymphoma and renal cell carcinoma were particularly sensitive to iron death regulated by GPX4." (PMID 36105937, 2022). "Gpx4-regulated ferroptosis is also highly sensitive to diffuse large B cell lymphomas and renal cell carcinomas, according to sensitivity profiling of 177 cancer cell lines." (PMID 35408533, 2022). "It has been shown that GPX4 and system Xc– are required for the survival of certain tumor cells, including renal cell carcinoma and diffuse large B cell lymphoma cells, and a characteristic ferroptotic death is observed in these cells upon GPX4 knockdown." (PMID 32984038, 2020). "Specifically, GPX4 knockdown using siRNAs decreases the level of GPX4 protein, a central mediator of ferroptosis, inducing renal cell carcinoma cell death with accompanying lipid ROS generation." (PMID 29375387, 2017). "Researchers suggest that future studies could explore NRF2 activity inhibitors applicable to humans or develop inhibitors targeting succinated GPX4 to induce ferroptosis in hereditary leiomyomatosis and renal cell cancer cells." (PMID 39021564, 2024). "Furthermore, Gpx4 knockdown results in ferroptosis in renal cell carcinoma cells, which is accompanied by an increase in lipid ROS." (PMID 35408533, 2022). "However, whether SLC7A11 and GPX4 serve as an oncogene in renal cell carcinoma (RCC) remains unclear." (PMID 37807410, 2023). "Renal cell carcinoma (RCC) is more sensitive to ferroptosis under an iron overload state and low GPX4 levels." (PMID 32908642, 2020). "Importantly, the expression level of GPX4, the most important regulator of ferroptosis, could markedly affect the renal cell carcinoma cell growth by regulating ferroptosis, and the ferroptosis could be reversed by the treatment of vitamin E and iron chelator desferrioxamine (DFO)." (PMID 36926345, 2023). "Based on the positive expression of SLC7A11 and GPX4 in RCC tissues, we preliminarily concluded that ferroptosis may play a role in the occurrence and progression of renal cell carcinoma." (PMID 37807410, 2023). "ZONs inhibited the expression of GPX4 and SLC7A11 and elevated the levels of Fe2+ and ROS in renal cell carcinoma (RCC) cells, which promoted the occurrence of ferroptosis in tumorigenic mouse models." (PMID 39276361, 2024).
renal cell carcinoma (continued). "Some cancers, like diffuse large B cell lymphomas and renal cell carcinomas, are very sensitive to GPX4-mediated ferroptosis, whereas others do not require functional GPX4 to survive, mostly due to upregulated antioxidant defense and decreased amount of fatty acids in cellular membranes." (PMID 38203246, 2023).
myocardial ischemia (22 papers, 2021 to 2025). A disorder of cardiac function caused by insufficient blood flow to the muscle tissue of the heart. "For instance, in myocardial ischemia–reperfusion injury, GPX4 was reported to undergo ubiquitination and subsequent degradation." (PMID 40943126, 2025). "Research has confirmed that hydroxysafflor yellow A (HSYA) can inhibit myocardial cell ferroptosis by activating HIF-1α, which ultimately increases the expression of SLC7A11 and GPX4, thereby reducing myocardial ischemia/reperfusion injury in mice." (PMID 40691131, 2025). "GPX4 overexpression ameliorated, whereas GPX4 heterodeletion exaggerated myocardial ischemia/reperfusion (I/R) injury and doxorubicin-induced cardiomyopathy in mice." (PMID 39318361, 2024). "During myocardial ischemia-reperfusion, the increase in intracellular free iron levels and the decrease in GPX4 activity lead to the massive release of ROS within myocardial cells, causing lipid peroxidation." (PMID 37383699, 2023). "Studies also demonstrated that naringenin alleviated myocardial ischemia/reperfusion injury by regulating the nuclear factor-erythroid factor 2-related factor 2/System xc-/glutathione peroxidase 4 (GPX4) axis to inhibit ferroptosis." (PMID 35664944, 2022). "In conjunction with the previous results, RSL3, a GPX4 inhibitor, was used to further investigate the protective role of C3G in myocardial ischemia-reperfusion." (PMID 33628391, 2021). "As an antioxidant enzyme, GPX4 undergoes ubiquitin-mediated degradation during myocardial ischemia–reperfusion injury; however, the role of its ubiquitination in DIC remains unclear." (PMID 40943126, 2025). "Recombinant human GPX4 alleviated ISO-induced myocardial ischemia injury." (PMID 36792890, 2023). "The specific mechanism is as follows: miR-135b-3p downregulates the expression of GPX4, leading to ferroptosis in cardiomyocytes and aggravating myocardial ischemia/reperfusion injury, which means that miR-135b-3p promotes cell death in an iron-dependent manner in vitro." (PMID 36187333, 2022). "Furthermore, it has been shown that naringenin alleviates myocardial ischemia/reperfusion injury by regulating the Nrf2/System xc-/GPx4 axis, while rutin induces glutathione peroxidase activity in cadmium-induced oxidative stress." (PMID 35807632, 2022). "Collectively, our study revealed the pathogenesis of oxidative stress and ferroptosis associated with myocardial ischemia, and indicated the antioxidant and anti-ferroptosis effects of GEN on preventing myocardial injury by activating the Grsf1/GPx4 axis, serving as a potential therapeutic target." (PMID 35600863, 2022). "The changes in GPX4 and FTH1 protein expression in mice with myocardial ischemia/reperfusion injury was consistent with the results in cells." (PMID 38926825, 2024). "In a myocardial ischemia–reperfusion injury model, isoliquiritigenin reduces oxidative stress and ferroptosis by promoting Nrf2 nuclear translocation and activating the expression of HO-1, SLC7A11, and GPX4." (PMID 40298739, 2025).
COVID-19 (21 papers, 2021 to 2026). A disease caused by infection with severe acute respiratory syndrome coronavirus 2. "Alongside the unfavorable effect of GPX4 activity loss, iron overload contributes to the pathogenesis of coronavirus disease-19 (COVID-19), inciting inflammation, hypercoagulation, and immune dysfunction." (PMID 37554293, 2023). "Low levels of the GSH in COVID-19 patients are associated with ferroptosis and with a down-regulation of GPX4 and TrxR." (PMID 35326383, 2022). "Selenium can also upregulate GPX4 to protect cells against ferroptosis in the stroke model and can be used for treating COVID-19 (NCT04869579, NCT04798677, NCT04751669 and NCT04323228)." (PMID 39516736, 2024). "The dysregulation of iron, the high levels of lipid peroxidation biomarkers, and the inactivation of GPX4 in COVID-19 patients make a strong case for ferroptosis as a potential mechanism behind post-COVID neuropsychiatric deficits." (PMID 37554293, 2023). "GSH levels and Gpx4 activity are maintained to counteract the tissue and organ damage caused by SARS-CoV-2 infection and to reduce the severity of COVID-19." (PMID 37303950, 2023). "Drugs that potentiate the GPX4-GSH axis, induce RTA and ACSL4 activity and, finally, cause labile pool iron depletion are likely candidates in COVID-19 treatment." (PMID 34829548, 2021). "In COVID-19 patients, altered iron metabolism, depletion of GSH, inactivation of GPX4, and up-regulation of lipid peroxidation biomarkers strongly propose ferroptosis as a plausible mechanism for COVID-19 multi-organ affection, including neuropsychiatric sequelae." (PMID 38641847, 2024). "Since the selenoprotein glutathione peroxidase 4 (GPX4) has been shown to be a major modulator of lipid peroxidation, we reasoned that COVID-19 serum could regulate its expression." (PMID 36829885, 2023). "In addition, scRNA-seq data from PBMC, T cells and B cells from COVID-19 patients showed that ferroptosis-related genes (including GPX4, FTH1, FTL and SAT1) were increased in the acute phase and decreased in the recovery phase." (PMID 36060261, 2022). "COVID-19 patients suffer from GPX4 depletion, confirming ferroptosis; the principal mechanism behind the anti-ferroptosis effect of vitamin E is that it can detoxify oxidized lipids compensating for the lack of detoxification derived from GPX4 deficiency." (PMID 36293182, 2022). "Neurodegeneration in COVID-19 patients is a potential consequence of GSH depletion and GPX4 inactivation, which would promote lipid peroxidation and ferroptosis." (PMID 38641847, 2024). "Intracellular iron capture to remove GSH, inactivate GPX4 and up-regulate PUFA peroxidation are components of SARS-CoV-2 infection and ferroptosis, indicating that ferroptosis plays an irreplaceable role in the pathogenesis of COVID-19 organ damage." (PMID 37809536, 2023). "In COVID-19 patients, altered iron metabolism, depletion of glutathione (GSH), inactivation of GPX4, and up regulation of lipid peroxidation biomarkers strongly propose ferroptosis as a plausible mechanism for COVID-19 multi-organ affection, including neuropsychiatric sequelae." (PMID 37554293, 2023). "In response to the ferroptosis manifestation of COVID-19, it has been suggested that drugs that enhance the GPX4-GSH axis, induce RTA and ACSL4 activity and ultimately lead to iron depletion in the unstable pool may be candidates for COVID-19 treatment." (PMID 36060261, 2022). "Since that COVID-19 exhibits unusual symptoms including GSH depletion, GPX4 inactivation, abnormal iron metabolism, and elevation of PUFA peroxidation by reactive oxygen species, it is possible that SARS-CoV-2 might cause ferroptosis in the dopaminergic neurons, which would then contribute to PD." (PMID 38503730, 2024).
COVID-19 (continued). "In addition, serum from coronavirus disease 2019 (COVID-19) non-survivors triggers ferroptosis in endothelial cells, which was manifested by elevated lipid peroxidation levels and decreased expression of GPX4, SLC7A11, and ferritin heavy chain (FTH1)." (PMID 39251905, 2024). "Leukopenia in COVID-19 patients may be related to ferroptosis in leukocytes and suppressed GPX4 caused by SARS-CoV-2.The lack of GPX4 induced the loss ability of GSH be peroxidized to minimize the lipid ROS produced by the Fenton reaction." (PMID 38503730, 2024). "Eventually, the T cells go into ferroptosis due to the lack of GPX4, resulting in a weakened body defense system unable to effectively defend against viral infections, which may be one of the crucial reasons for COVID-19 progressing to severity." (PMID 37303950, 2023). "Thus, we measured GPX4 in HUVECs, both at the mRNA and at the protein level, and we found that a 24 h incubation with serum obtained from patients who did not survive COVID-19 significantly decreased GPX4 expression." (PMID 36829885, 2023). "Moreover, it has been proposed that drugs that enhance the GPx4-GSH axis and ultimately lead to iron depletion in the unstable pool may be candidates for COVID-19 treatment in response to the ferroptosis manifestation." (PMID 36978981, 2023). "In addition, the expression of the anti-ferroptosis genes GPX4 and FSP1 was not significantly changed in COVID-19 lungs." (PMID 38769293, 2024).
epilepsy (21 papers, 2019 to 2025). A brain disorder characterized by episodes of abnormally increased neuronal discharge resulting in transient episodes of sensory or motor neurological dysfunction, or psychic dysfunction. "Lipid peroxidation and ferroptosis caused by loss of Glutathione peroxidase 4 (GPx4) have also been demonstrated in epilepsy models." (PMID 40709096, 2025). "Deletion of GPX4, an essential regulator of ferroptosis, has been found to induce susceptibility to epilepsy." (PMID 38191407, 2024). "Elevated levels of intracellular iron ions (Fe3+ and Fe2+) will produce a large amount of ROS and affect various biological pathways, including those involving GSH, GPX4, and lipid peroxidation, leading to an increased susceptibility to epilepsy." (PMID 37621773, 2023). "The critical features of ferroptosis have been observed in the models of AD, epilepsy, stroke, and Parkinson’s disease (PD), including loss of glutathione, increased ROS, decreased GPX4, and lipid peroxidation." (PMID 33424539, 2020). "Thus, we hypothesize that the microRNA-211-5p/P2RX7/ERK/GPX4 axis might regulate epilepsy-associated neuronal ferroptosis and oxidative stress." (PMID 38191407, 2024). "As epilepsy is commonly associated with mitochondrial disease, targeting GPX4 to stimulate the enzymatic removal of lipid hydroperoxides could present a potential interventional strategy for mitochondrial disease-associated epilepsy, such as pontocerebellar hypoplasia type 6." (PMID 32585915, 2020). "Accordingly, targeting either 15-LO with the intent to decrease the formation of lipid peroxides or GPX4 to increase the catalytic clearance of lipid hydroperoxides represent rational therapeutic approaches to modulate ferroptosis as an intervention for mitochondrial disease-associated epilepsy." (PMID 30921410, 2019). "Evidence for ferroptosis as an underlying facet of epilepsy is emerging from mouse genetic models with seizure phenotypes, particularly those in which the function of the essential phospholipid hydroperoxide-reducing GPX4 enzyme was targeted directly or indirectly." (PMID 30921410, 2019). "Specifically, AST activates the Nrf2/GPX4 signaling pathway to regulate glutathione metabolism and inhibit ferroptosis, offering a novel therapeutic strategy for targeting epilepsy." (PMID 39957487, 2025). "Consistent with our findings, we observed abnormal expression of ferroptosis‐related proteins ACSL4, PTGS2, and GPX4 in the hippocampal tissues of KA‐induced epileptic mice, indicating the involvement of ferroptosis in epilepsy." (PMID 39957487, 2025). "The AST effectively inhibits neuronal ferroptosis in both in vivo and in vitro epilepsy models via the Nrf2/GPX4 pathway." (PMID 39957487, 2025). "In summary, this study aims to explore the neuroprotective mechanism of AST against KA‐induced epilepsy in mice by examining the ferroptosis through the Nrf2/GPX4 signaling pathway." (PMID 39957487, 2025). "As a critical regulator, glutathione peroxidase 4 (GPX4) has been demonstrated to be downregulated in epilepsy." (PMID 38191407, 2024). "In our study, P2RX7 blockade regulated GPX4/HO-1 by suppressing the ERK cascade in murine models of epilepsy." (PMID 38191407, 2024). "In contrast to the control group, there was a significant decrease in the expression of GPx4 in the epilepsy group (control: 1, epilepsy: 0.62 ± 0.09, p < 0.05)." (PMID 38357854, 2024). "Although some evidence has confirmed the role of ferroptosis in the pathogenesis of epilepsy and that reversing the downregulation of GPX4 can effectively delay the course of epilepsy, the existence of ferroptosis in epilepsy still needs more verification." (PMID 38191407, 2024). "Since GPX4 is a selenium-dependent enzyme for interneuron growth and seizure prevention, these findings provide evidence for the crucial role of GPX4 in epilepsy." (PMID 38499882, 2024).